THY1 (Thy-1 cell surface antigen)
Diseases named in the same sentence as THY1 in open-access papers (continued):
Sharing a sentence is not in itself a finding about the gene and the disease.
glomerulonephritis (continued). "In anti-Thy-1 glomerulonephritis, the induction of minor podocyte injury with PAN pretreatment results in an irreversible mesangial alteration." (PMID 21251296, 2011). "Enhancing NO production by supplementing the substrate L-arginine improves theclinical course of anti-Thy-1-glomerulonephritis." (PMID 19266048, 2008). "However, our result clearly demonstrated the beneficial effect of using everolimus as an immunosuppressant drug to reduce renal inflammation and damage in anti-Thy1-induced glomerulonephritis." (PMID 35008770, 2021). "Anti-thy1 glomerulonephritis was induced into male Wistar rats by OX-7 antibody injection." (PMID 27243813, 2016). "Suppression of PAI-I mRNAs in experimental animals after administration of PAI-1 inhibitors have been also demonstrated previously in other kidney disease models, such as the anti-Thy-1 rat glomerulonephritis model as well as in the rodent multiple sclerosis model." (PMID 27258009, 2016). "In the anti-Thy1 glomerulonephritis rat model, we detected miR-34a expression in kidney tissues at various time points and found that miR-34a level gradually decreased as proliferation increased, then returned to normal levels when mesangial proliferation normalized." (PMID 24638095, 2014). "In this model, injection of high dose anti-thy1 antibody into uninephrectomized rats leads to a brief period of acute mesangioproliferative glomerulonephritis which is followed by an autonomous progression towards glomerulosclerosis, tubulointerstitial fibrosis and renal insufficiency over months." (PMID 24119229, 2013). "The novel finding of this study is that expands from the acute anti-thy1 glomerulonephritis into a anti-thy1-induced chronic-progressive glomerulosclerosis model of human mesangioproliferative nephropathy as a leading cause of end-stage kidney disease worldwide." (PMID 24119229, 2013). "Previous studies have shown that beneficial effects of Imatinib in some models of renal fibrosis, such as acute anti-thy1 glomerulonephritis of the rat, lupus nephritis, hypertensive nephropathy, diabetic nephropathy, unilateral ureteral obstruction, chronic allograft nephropathy." (PMID 24119229, 2013). "The studies in anti-thy1 acute and chronic renal disease unanimously indicate that unaffected mTOR signaling is critical for the very early and marked mesangial cell proliferation and subsequent normal glomerular repair of acute anti-thy1 glomerulonephritis." (PMID 22685654, 2012). "In addition, cysteine-rich protein 61 (Cyr61), a potent angiogenic protein that belongs to the CCN family of matrix-associated secreted protein family, is expressed in podocytes and upregulated in anti-Thy-1 glomerulonephritis." (PMID 21251296, 2011). "Innondiabetic animals, beneficial effects have been shown for anti-GBMantibody-induced crescentic glomerulonephritis,passive Heymann nephritis,the development of glomerulosclerosis after 5/6 nephrectomy,renal ischemia-reperfusion induced damage, and anti-Thy-1-glomerulonephritis." (PMID 19266048, 2008). "Furthermore, we found an up-regulation of the pro-inflammatory cytokine IL-6 on d5 of acute anti-thy1 glomerulonephritis, confirming recent experimental studies which demonstrated convincingly that IL-6 is a strong mediator of mesangial cell proliferation and matrix expansion in glomerulonephritis." (PMID 27243813, 2016). "Given that impairment of cGMP-signalling leads to anti-thy1 glomerulonephritis, and the cGMP-signal transduction pathway has been shown to abate inflammation, the enhancement of ANP and cGMP by hemin may counter-regulate the effects of elevated renal inflammation to improve renal function." (PMID 24498225, 2014). "In this sense, the model of anti-thy1-induced, chronic progressive renal fibrosis may be seen as representation of patients with primary glomerular disease who progress to end-stage renal disease after a single episode of glomerulonephritis." (PMID 24119229, 2013).
glomerulonephritis (continued). "Future studies will focus on using higher doses of BMDSCs vs. repeated administration of the currently used bolus dose of BMDSCs to determine why BMDSCs failed to provide renal protection in anti-Thy1-induced glomerulonephritis." (PMID 35008770, 2021). "Our data suggest that i.v. bolus administration of BMDSCs did not improve anti-Thy-1-induced glomerulonephritis and renal apoptosis, although it did reduce the expression of renal T cells, macrophages and IL-17." (PMID 35008770, 2021). "Interestingly, THY1 is also involved in regulating collagen type I, smooth muscle alpha actin, and TGF-β1 in the renal glomerulus from rats exhibiting glomerulonephritis." (PMID 19513121, 2009). "Nevertheless, another study of rat models of acute and chronic progressive anti-thy1 glomerulonephritis suggested that moderate alcohol consumption might not bring specific protection in renal fibrotic disease." (PMID 37286970, 2023).
prostate carcinoma (24 papers, 2008 to 2026). A carcinoma that arises from epithelial cells of the prostate gland. "In this context, it is interesting to note that PTGS1 methylation is frequent in prostate cancer, THY1 has been implicated as a candidate TSG in nasopharyngeal cancer and SST promoter methylation has been described in ∼90% of colorectal cancers." (PMID 18195710, 2008). "High expression of THY1 in ECs is associated with poor prognosis across various cancers 53, and the increase in vascular ECs post-treatment likely provides essential blood supply to residual tumors, which may contribute to prostate cancer recurrence following hormonal therapy." (PMID 41041045, 2025). "The percentage of THY1+ cells was significantly increased within the stroma adjacent to Gleason 4 prostate cancer with cribriform morphology compared to stroma adjacent to benign prostate glands." (PMID 33600062, 2021). "ASPN+ cells enriched in cribriform prostate cancer were also THY1+." (PMID 33600062, 2021). "A subset of cases probed for ASPN expression were also dually examined for THY1 expression in stroma adjacent to benign prostate (n = 10) and in Gleason grade 3 (n = 6), Gleason grade 4 with noncribriform morphology (n = 6), and Gleason grade 4 with cribriform morphology (n = 7) prostate cancer." (PMID 33600062, 2021). "We also show that SKP2 overexpression in prostate cancer PC3 cells increases the protein levels of TWIST1 and the expression of EMT related genes, including FMOD, THY1, NFIL3 and IRF2, leading to a marked increase in migration and invasion." (PMID 41542047, 2026). "RNA from a dilution series of prostate cancer lines C4-2 and PC3 was prepared, and hybridized to a probe library of six selected genes: KLK3, CD90/THY1, AGR2, HPN, PCA3, UPK3A." (PMID 23029164, 2012).
glioblastoma (21 papers, 2011 to 2025). The most malignant astrocytic tumor (WHO grade IV). "Thy-1 expression in glioblastoma vasculature is associated with endothelial, smooth muscle, and pericyte cells, supporting Thy-1 function during angiogenesis." (PMID 35186924, 2022). "The impairment of HCMV infectivity following knockdown of THY-1 was observed in glioblastoma (SNB-19), adenocarcinoma (HS-578T) and MRC-5 cells infected with either epithelial/endothelial or fibroblast tropic HCMV." (PMID 26147640, 2015). "The final cell type common to all three specimens was characterised by expression of PDGFRB (PDGFRβ/CD140b), MCAM (CD146), THY1 (CD90), FN (fibronectin) and type IV collagen genes, markers typical of mature pericytes, including those in normal human brain and glioblastoma." (PMID 33082953, 2020). "With respect to GBM, recent studies have shown that several antigens including cluster of differentiation 90 (CD90, Thy-1) and GD2 disialoganglioside are frequently overexpressed in glioblastoma cells." (PMID 28178667, 2017). "THY1/CD90 has been suggested as a microenvironment sensor in different cancers, including lung and glioblastoma." (PMID 35172861, 2022). "THY1 (CD90) is a surrogate marker for a variety of stem cells, including glioblastoma stem cells (GSC) and GASC." (PMID 33996602, 2021). "This includes expression of PDGFR‐β/CD140b, MCAM/CD146, Thy‐1/CD90, fibronectin and several collagen genes, all of which have emerged as reliable markers of human pericytes in normal brain and glioblastoma." (PMID 33082953, 2020). "NCI-60 cell lines SNB-19 (glioblastoma) and HS-578T (adenocarcinoma), as well as primary human diploid (MRC-5) fibroblasts all express THY-1 mRNA, and THY-1 protein was detected on the surface of these cells." (PMID 26147640, 2015).
rheumatoid arthritis (19 papers, 2013 to 2025). A chronic, systemic autoimmune disorder characterized by inflammation in the synovial membranes and articular surfaces. "Mechanistically, these expanded inflammatory Thy1+ fibroblasts were shown to drive inflammation in rheumatoid arthritis by secreting IL6 and chemokines such as CCL2, CX3CL1, CXCL9, and CXCL12." (PMID 35085231, 2022). "As for rheumatoid arthritis synovial fibroblasts, stable epigenetic modifications particularly on fibroblast genes like ACTA2 and THY1 (encoding for αSMA and CD90, respectively), also contribute to the progression of fibrosis." (PMID 36793548, 2022). "In other inflammatory diseases such as rheumatoid arthritis, fibroblasts also show overexpressed Thy-1/CD90 levels in cells located at the inflamed synovium." (PMID 31428610, 2019). "Thus, PDPN+FAPα+THY1+ cells play the role of an immune effector in the development of rheumatoid arthritis, capable of maintaining inflammation through the secretion of a different repertoire of chemokines and cytokines, as PDPN+FAPα+THY1− cells are capable of regulating osteoclast behavior." (PMID 38136590, 2023). "Similarly, in the context of rheumatoid arthritis, chronic inflammation was shown to drive differentiation of synovial fibroblasts (CD34− Thy1+) that share many features with IAFs." (PMID 35085231, 2022).
Cognitive impairment (17 papers, 2013 to 2025). Abnormal cognition is characterized by deficits in thinking, reasoning, or remembering. "A rat model with a doubly mutated APP, driven by a Thy1.2 promoter highly expressed in neurons, triggered the accumulation of intraneuronal human Aβ in 2–3-month-old rats, coinciding with cognitive impairments and pre-plaque generation." (PMID 31685865, 2019). "In this study, first we confirmed that 9-10 months old APP/PS1 mice (carrying transgenes for both APP bearing the Swedish mutation and PSEN1 containing an L166P mutation, both under the control of the Thy1 promoter) display short-term memory and cognitive deficits." (PMID 36937050, 2023). "We then assessed cognitive impairment in the following 4 genotypes: Bin1flox/flox:: Thy1-Cre+:: PS19Hemi, Bin1flox/flox::Thy1-Cre-::PS19Hemi, Bin1flox/flox:: Thy1-Cre+:: PS19Ncar, Bin1flox/flox::Thy1-Cre-::PS19Ncar." (PMID 31408457, 2019). "We followed by validating cognitive impairment in the Thy1-aSyn mice." (PMID 38615035, 2024). "Importantly, we show that the hippocampal cofilin pathology triggered by αSyn co-manifests with synaptic dysfunction and cognitive impairment in vivo by using the Thy1-aSyn mice, a suitable model to study cognitive deficits in the context of LBD." (PMID 38615035, 2024). "Our in vivo results are partially in line with those of a previous study by Subramaniam and colleagues that investigated the effects of nicotine treatment in tg mice overexpressing human α-Syn under the Thy-1 promoter and reported improvement of cognitive impairment after chronic nicotine treatment." (PMID 37719154, 2023). "In particular, cognitive deficits have been detected in the Y-maze, novel object recognition and operant reversal learning tests in transgenic mice overexpressing human wild-type a-syn under the Thy1 promoter." (PMID 23705016, 2013). "As synaptic dysfunction is one of the key mechanisms associated with cognitive deficits in dementia, we investigated the effect of rTMS on cortical synapses using an APP/PS1 amyloidosis mouse model of AD crossed with fluorescent reporters linked to the Thy-1 promoter." (PMID 40438149, 2025). "This widely used AD model [Tg(Thy1‐APPSw, Thy1‐PSEN1*L166P) 21Jckr] typically shows amyloid deposition in the hippocampus at 3–4 months and cognitive impairment at 7–8 months of age." (PMID 27485122, 2016). "Mice overexpressing wild-type alpha-synuclein under the Thy-1 promoter (Thy1-aSyn, line 61) uniquely replicate early cognitive deficits together with multiple other characteristic motor and non-motor symptoms, alpha-synuclein pathology and dopamine loss." (PMID 34307368, 2021). "Among the transgenic models, the mice expressing human wild type α-syn under the Thy1 promoter have been consistently reported to exhibit non-motor phenotypes that are relevant to PD, such as cognitive impairment, olfactory dysfunction, constipation and changes in the circadian rhythm." (PMID 34361100, 2021).
synucleinopathy (16 papers, 2013 to 2026). A neurodegenerative disease that is characterized by the abnormal accumulation of aggregates of alpha-synuclein protein in neurons, nerve fibers or glial cells. "The present report extends this observation to include murine models of synucleinopathies that harbor WT alleles of Gba1 (e.g. Thy1-SNCA transgenic mice)." (PMID 27126635, 2016). "To test our hypothesis that glycation-induced dysfunction of neuronal pathways might be an underlying molecular cause of synucleinopathies, we used Thy1-aSyn mice as a model of synucleinopathy." (PMID 35468899, 2022). "Finally, the (Thy-1)-[A30P]-hα-synuclein mouse model is well known to express supraphysiological levels of a human pathogenic variant of α-synuclein, well beyond the expression levels usually observed in patients suffering from α-synucleinopathies." (PMID 37322068, 2023). "While detailed characterization of the microglia in Thy1-aSyn L61 mice is limited, previous studies have described the gradual development of α-synucleinopathy accompanied by age-dependent neuroinflammation, which supports this interpretation." (PMID 41596612, 2026). "Follow-up investigations should be conducted in established synucleinopathy in vivo models, such as Thy1-SNCA transgenic mice, to rigorously assess the effects of rHsCTSB and rHsCTSL on disease-relevant phenotypes and behavioral outcomes." (PMID 40883786, 2025). "We used a progressive mouse model of synucleinopathies using mice overexpressing human wild-type α-syn driven by the murine Thy-1 promoter." (PMID 41258081, 2025). "The hSyn mouse, which overexpresses human WT α-Syn under the neuron-specific Thy-1 promoter, develops progressive neuropathological and behavioral deficits closely resembling synucleinopathies." (PMID 41377958, 2025). "Conversely, augmenting glucocerebrosidase activity in the Thy1-SNCA mouse model of PD delayed the progression of synucleinopathy." (PMID 27126635, 2016). "Previous studies revealed hyperactivity of young (4–7 months of age) Thy1-aSyn mice in the open field, an effect observed in several mouse models of synucleinopathies at a young age." (PMID 25505609, 2014). "Even though a genetic lack of tau did not improve motor deficits in mice overexpressing α-synuclein under the Thy-1 promoter (Thy1-aSyn mice), in a cellular model of synucleinopathy, tau enhanced aggregation and toxicity of α-synuclein." (PMID 25505609, 2014). "The present study shows that Thy1-aSyn mice, a model of synucleinopathy, have impaired baroreflex control of HR analogous to what is observed in patients with the synucleinopathy PD." (PMID 23888153, 2013). "In the present study, the baroreceptor reflex was assessed in mice overexpressing human wildtype alpha-synuclein (Thy1-aSyn), a genetic mouse model of synucleinopathy." (PMID 23888153, 2013). "To address this hypothesis, we used a synucleinopathy mouse model, which overexpresses human wild-type α-syn under the murine Thy1 promotor, and administrated 11R-VIVIT, a selective cell-permeable NFAT1 inhibitor." (PMID 41258081, 2025). "In the current study, we used Xenium, a subcellular-resolution imaging spatial transcriptomic (IST) platform, with a well-characterized transgenic synucleinopathy mouse model which overexpresses wild-type human α-synuclein (hSNCA) under the murine neuronal Thy1 promoter (Line 61, α-syn-tg)." (PMID 39372781, 2024). "Furthermore, we demonstrated positive staining for CD3+ in the midbrain of the transgenic synucleinopathy model of PD (mice overexpressing human wild-type α-synuclein [WTS] under the Thy1 promoter [Thy1-WTS])." (PMID 29078813, 2017). "These antibodies were used to determine the exposed epitopes of alpha-synuclein monomers and fibrils generated in vitro, as well as inclusions in brain tissue sections from a transgenic (Thy-1)-h[A30P] alpha-synuclein mouse model and from patients with alpha-synucleinopathies." (PMID 28028735, 2017).
synucleinopathy (continued). "Thus, the Thy1-aSyn mice show a potentially broader range of autonomic anomalies than previously reported in other mouse models of synucleinopathy." (PMID 23888153, 2013). "To this end, we analyzed adult hippocampal neurogenesis in two transgenic mouse models of α-synucleinopathy, overexpressing WTS and E57K-mutant a-syn under control of the Thy1 promoter." (PMID 29124353, 2018). "In the Thy1-WTS transgenic mouse model, characterized by pronounced synucleinopathy, we previously showed that CNS-invading CD3+ T lymphocytes contribute to the PD pathogenesis by modulation of CNS myeloid cell activation." (PMID 29078813, 2017). "In the substantia nigra, a region majorly affected in synucleinopathies, no cofilin pathology was observed, although robust levels of αSyn are expressed in that brain region in the Thy1-aSyn mice." (PMID 38615035, 2024). "In the present study, we used a well-characterized mouse model of α-synucleinopathy (Line 61, α-syn-tg) which overexpresses wild-type human α-synuclein (hSNCA) under the murine Thy1 promoter, and non-transgenic littermate controls (non-tg)." (PMID 39372781, 2024).